IL13 (interleukin 13)
Diseases named in the same sentence as IL13 in open-access papers (continued):
Sharing a sentence is not in itself a finding about the gene and the disease.
type 2 diabetes (15 papers, 2012 to 2025). "Furthermore, recent studies on prediabetic subjects suggest that the level of IL-13 is negatively associated with risk of type 2 diabetes and can be considered as an anti-inflammatory marker for incidence of T2DM and insulin resistance." (PMID 32948777, 2020). "Thiazolidinediones (TZDs), an FDA-approved class of PPAR agonists used to manage type 2 diabetes, improved the outcomes of anti-IL-4/IL-13 for treating AD in obese mice by reducing immunological misfiring." (PMID 36614274, 2023). "In this sense, it has been previously shown that serum levels of IL-13 are significantly reduced in type 2 diabetic patients with coronary artery disease as compared to healthy controls." (PMID 29675435, 2018). "In age and sex adjusted model, EN-RAGE, IL13, IL17, complement 3, IL18, TNFRII, IL1ra and CRP were associated with incident type 2 diabetes." (PMID 28258520, 2017). "In multivariate models, IL13 (HR = 0.67), IL17 (HR = 0.76) and CRP (HR = 1.32) remained associated with incident type 2 diabetes." (PMID 28258520, 2017). "Similarly, a recent study demonstrated that type 2 diabetic patients show decreased serum levels of IL-13 with respect to normal-glucose tolerant individuals." (PMID 29675435, 2018). "Based on our results, plasma levels of IL13 may be informative in Type 2 diabetes research." (PMID 36647296, 2016). "While IL-1β, glucagon and Apo-B are individual markers for type 2 diabetes, PDGF-BB, IL-13, eotaxin, Apo-E, and Apo-CII are the individual markers for the CAD group." (PMID 30674322, 2019). "This study only indicates new associations, emphasizing the need for further studies to establish the role of EN-RAGE, IL13 and IL17 in the development of type 2 diabetes." (PMID 28258520, 2017).
Cognitive impairment (14 papers, 2020 to 2026). Abnormal cognition is characterized by deficits in thinking, reasoning, or remembering. "More recently, Serre-Miranda and colleagues (2020) associated high plasma levels of IL-13 with “Poor” cognitive performance, thus pointing out the possibility of a cognitive impairment in Fr female." (PMID 36289502, 2022). "Although the level of sTNFRII was found to be associated with subjective cognitive complaints in BC patients with or without chemotherapy, no previous reports were found in the associations of IL-5 or IL13 and subjective cognitive impairments." (PMID 34073990, 2021). "The literature on our finding of IL-13 associations with learning and/or memory is still scarce and inconsistent, and no previous research has discussed its role in cancer-related cognitive impairment." (PMID 34073990, 2021). "In this regard, a relevant observation is the consistency of the elevation of inflammatory cytokines IL-6, IL-13, IL-8, IL-1β, and TNFα at the longest phase of follow-up related to cognitive deficits and/or post-acute sequelae." (PMID 41516418, 2026). "In an amyloid precursor protein (APP) mouse model for AD—APP23, intracerebral injection of IL-4/IL-13 increases Aβ clearance and improves cognitive deficits." (PMID 39769453, 2024). "Many BafA1- or Rapa-induced up-regulated pro-inflammatory cytokines (e.g., IL-1B, TNFs, IL10, IL12, and IL13), correspond to the presence of CNS pathologies like cognitive impairment observed in patients with meningitis." (PMID 32225060, 2020). "Remarkably, IL-4 and IL-13 can activate microglia, the pivotal sources of inflammatory factors and oxidative stress in the brain, to induce Aβ degradation and improve cognitive impairment." (PMID 32382304, 2020). "Thus, inflammatory cytokines IL-6, IL-1β, IL-13, and TNFα are elevated at this longer phase and are related to cognitive deficits and/or post-acute sequelae." (PMID 41516418, 2026). "The MGCs, Mφs, and sera of the PARK2 mouse model displayed decreased expression of parkin and its link to the increased generation of pro-inflammatory cytokines and chemokines (e.g., IFNβ1, TNFα, IL-1β, IL-12, IL-13, IL-17, CCL2, and CXCL1), loss of DA neurons, and cognitive defects in PD." (PMID 34239490, 2021). "Increasing evidence suggests that flavonoids could ameliorate allergic inflammation by suppressing IL-4 and IL-13 production following the release of basophils and histamine, and improve the cognitive impairment of patients with neurodegenerative disease by inhibiting TNF-α and IL-6 release." (PMID 37292198, 2023). "Additionally, PARK6-associated PD patients have also shown PINK1 deficiency and its impact on increased generation of pro-inflammatory cytokines and chemokines (e.g., IFNβ1, IL-6, IL-12, IL-13, CCL2, CCL4, and CXCL1), loss of NCs, and the development of cognitive defects." (PMID 34239490, 2021). "Also, by restoring type 2 signaling through therapeutic injection of IL-33, IL-4 or IL-13, or augmenting hippocampal IL-4 with phosphatidyl serine, neurosynaptic function might be preventatively enhanced or bolstered in mild cognitive impairment or in early AD." (PMID 39071802, 2024). "In addition, the IL-13 release in vitro was significantly increased from CD4+ T cells isolated from the MCI patients compared to those from patients without cognitive impairment." (PMID 37373554, 2023).
keloid (14 papers, 2020 to 2026). An irregularly shaped, elevated mark on the skin caused by deposits of excessive amounts of collagen during wound healing. "Expression levels of IL-4 and IL-13 tended to be higher in the peripheral regions compared to the central regions of both anterior chest and auricular keloids." (PMID 40830367, 2025). "It is evident from the literature that the TH2 inflammatory axis plays an integral role in keloid pathogenesis, with IL‐4 and IL‐13 serving as key mediators." (PMID 39895409, 2025). "IL-13 induced marked up-regulation of total collagen and type I collagen generation from keloid fibroblasts." (PMID 39799030, 2025). "To investigate pruritus mediators in keloids, we analysed the Th2 cytokines, IL-4, IL-13, and IL-31, and SP neuropeptide gene expression in anterior chest keloids, ear keloids, and normal skin using real-time PCR." (PMID 40830367, 2025). "Further, we identified downregulation of IL-13RA2, a decoy receptor for IL-13, in keloid fibroblasts compared with fibroblasts from normal dermis." (PMID 36757802, 2023). "Thus, the reduction of cDC2 in keloids may be associated with the downregulation of IL-13 expression, and the possible inappropriate inflammatory response associated with the downregulation of IL-13 expression is consistent with the pathogenesis of keloids." (PMID 35990663, 2022). "Other cytokines, such as IL33, IL-13, IL-10 and IL-4 have also been noticed increased in keloids." (PMID 41556665, 2026). "Interleukin 4 and IL‐13 (TH2 response) are overexpressed in patients with keloids." (PMID 39895409, 2025). "IL-13 modulates collagen homeostasis in human skin and keloid fibroblasts." (PMID 39799030, 2025). "As the master transcriptional regulator of Th2 differentiation, GATA3 directly transactivates IL-4, IL-5, and IL-13 genes, creating a profibrotic cytokine milieu that may contribute to keloid pathogenesis." (PMID 40718487, 2025). "In addition, increased expression of IL-4 and IL-13 was observed in the peripheral regions of keloids." (PMID 40830367, 2025). "We thus speculate that increased stiffness coordinates with IL-13 in the microenvironment to drive M2 polarization in keloids." (PMID 36757802, 2023). "Above all, dupilumab, which targets the IL-4/IL-13 pathway, may provide a better treatment choice for keloid patients, especially those with concurrent AD, and is worthy of further large-scale clinical trials." (PMID 37895153, 2023). "Th2 cells also mediate pruritus in keloids by producing IL-4 and IL-13." (PMID 37895153, 2023). "IL-13, a key driver of progressive fibrosis, has been found to be elevated in keloid patients." (PMID 36757802, 2023). "The expression of IL-4, IL-13 and their respective receptors is enhanced in keloid scars." (PMID 37033989, 2023). "This evidence suggests that Th2 cells and their cytokines, especially IL-4 and IL-13, contribute to keloid development, and the Th2 axis may become a breakout area of research in keloid pruritus treatments." (PMID 37895153, 2023). "In keloids, the pro-proliferative effects occur via the decoy effect of IL13RA2 and reduced IL13RA2 leads to accelerated IL13-induced fibrosis through STAT6." (PMID 40663259, 2025). "Numerous cytokines, such as IL-4, IL-6, IL-10, IL-12, IL-13, IL-17, TNF-α, and TGF-β, are markedly elevated in the keloid local microenvironment." (PMID 37895153, 2023). "In the present study, we have found that IL-13 signaling and the downstream JAK/STAT6 pathway are activated by the downregulation of IL-13RA2 in keloids." (PMID 36757802, 2023). "Among the DEGs involved in the IL-13 signaling pathway identified by the KEGG analysis, CXCL8 was recently confirmed to play an important role in keloid scar formation." (PMID 35082796, 2021). "In addition, the factors related to Th1, Th2, and Th17 cells such as IL4/IL13, IL17A/IL22, ADAM33, IFN-γwere upregulated overall in keloid and AD." (PMID 38476235, 2024).
keloid (continued). "IL-4 and IL-13 not only promote ECM deposition, inflammation, and pruritus of keloids but also induce the transformation of monocytes into M2 macrophages, thus playing a pivotal role in the pathogenesis of keloids." (PMID 37895153, 2023).
ovarian carcinoma (14 papers, 2007 to 2025). A malignant neoplasm originating from the surface ovarian epithelium. "Also, the high levels of IL-13 were associates with several tumor types such as head and neck carcinoma, Kaposi’s sarcoma, renal carcinoma, and ovarian cancer." (PMID 32899735, 2020). "In a mouse model of human ovarian cancer, IL-13 was reported to promote metastatic activities through the high-affinity IL-13 α2 receptor." (PMID 33922465, 2021). "IL-13 activated ERK1/2 signaling first followed by AP-1 activation through IL-13Rα2 in ovarian cancer cell lines, which in turn led to induction of MMP in IL-13Rα2 positive tumors." (PMID 30572904, 2018). "By these routes of administration, IL-13 cytotoxin mediated dramatic antitumor effects in very large established s.c. xenografted tumors and therefore, IL-13 is a promising target for ovarian cancer therapy." (PMID 19949545, 2009). "However, another study showed that induction of IL-13 via IL-33 injection delayed murine ID8 ovarian cancer progression." (PMID 33922465, 2021). "In addition, we have demonstrated that IL-13 can mediate signaling through IL-13Rα2 in human pancreatic and ovarian cancer cells." (PMID 30572904, 2018). "Human breast and renal cancer cell lines treated with exogenous IL-13 in vitro demonstrate reduced proliferation – although an ovarian cancer line demonstrated enhanced invasive and enzyme (protease) activity suggesting IL-13 aids primary tumor invasion and metastasis in this model." (PMID 25101088, 2014). "By these routes of administration, IL-13 cytotoxin mediated dramatic antitumor effects in very large established s.c. xenografted tumours and therefore, IL-13 has been proposed as promising target for ovarian cancer therapy." (PMID 19384429, 2007). "Other signaling pathways such as IRS1/2, PI3 K and AKT were not involved in IL-13 signaling in ovarian cancer cell lines." (PMID 30572904, 2018). "In addition, since IL-13/IL-13Rα2 axis is involved in AP-1 signal transduction pathway in human GBM similar to pancreatic and ovarian cancer, we believe that specific targeting of this pathway may be an important target for therapeutic intervention for GBM therapy." (PMID 30572904, 2018). "We also demonstrated that IL-13/IL-13Rα2 axis is functional in mediating ERK1/2, AP-1 and matrix metalo-proteinase (MMP) activities only in IL-13Rα2-positive cells but not in IL-13Rα2-negative ovarian cancer cells." (PMID 30572904, 2018).
cryptococcal infection (13 papers, 2011 to 2025). "Th2 responses are typically non‐protective against cryptococcal infection and are associated with the release of the inappropriate cytokines IL‐4, IL‐5 and IL‐13, which promote fungal persistence, dissemination and worsened pathology." (PMID 36175380, 2023). "Th2-type T-cell responses, characterized by production of IL-4 and IL-13 and alternative activation of macrophages, are strongly associated with adverse outcomes in mouse models of cryptococcal infection." (PMID 25853653, 2015). "Previous research has shown that suppressing the Th2 response by knocking out IL‐4, IL‐4R and IL‐13 in mice increases resistance to cryptococcal infection, with very little infiltration or persistence of fungal cells in the CNS compared to wild type." (PMID 36175380, 2023). "In contrast, Th2 responses (characterized by the production of IL-13) are harmful to the host during cryptococcosis (26, –, 28)." (PMID 36719231, 2023). "While type-1 immune responses have been shown to drive protective immunity against cryptococcal infection, type 2-skewed immune responses defined by the production of IL-4, IL-5, and IL-13 play deleterious roles in infection with C. neoformans." (PMID 30520685, 2019). "We further examined the effect of IFNAR1 deficiency on the Th2 response by measuring the production of IL-4, IL-5, and IL-13 in the lungs on day 3, 7, 14, and 28 after cryptococcal infection." (PMID 26384031, 2015). "Unexpectedly, however, Th2 cytokines such as IL-4 and IL-13, which suppress host defense against cryptococcal infection by inhibiting macrophage activation and enhancing mucin production, were not increased but rather also decreased in luCldn-18−/− mice compared to luCldn-18+/+ mice." (PMID 34702961, 2021). "Our analysis focused on identifying IFNgamma production as hallmark of Th-1 responses and improved outcomes in cryptococcal infection, and IL-13 as a marker of a non-protective Th2 response." (PMID 31247052, 2019). "Pulmonary cryptococcal infection resulted in a progressive accumulation of Cda2-MHCII-specific T cells in the lungs that predominately expressed the Th2 cytokines IL-5 and/or IL-13." (PMID 25764512, 2015).
Cirrhosis (12 papers, 2014 to 2025). A chronic disorder of the liver in which liver tissue becomes scarred and is partially replaced by regenerative nodules and fibrotic tissue resulting in loss of liver function. "In cases of HCC associated with MASLD-related cirrhosis, patients exhibited higher levels of fecal calprotectin and plasma levels of IL-8, IL-13, CCL3, CCL4, and CCL5 compared to those with MASLD-induced cirrhosis without HCC." (PMID 39451600, 2024). "Also, Liu and his colleagues reported that markedly elevated protein expression of IL-13 was detected in patients with HCV-associated cirrhosis which could elucidate the elevated P-selectins in patients with HCV." (PMID 25066324, 2014). "A higher trend of pro-inflammatory cytokines including IL-1α, IL-1β, IL-6, IL-8, IFN-γ and TNF-α was detected in the plasma from ACLF patients than that from cirrhosis patients, as well as the anti-inflammatory cytokines including IL-4, IL-10 and IL-13." (PMID 37380987, 2023). "IL-13 is also involved in mediating allergic reactions, suggesting the profibrotic potential of IL-13 and widespread immunomodulatory disturbances that are prevalent in cirrhosis." (PMID 36743413, 2023). "Interestingly, iNKT cells from patients with HCV-related cirrhosis showed a marked increase in the production of pro-fibrotic IL4 and IL13, suggesting that iNKT cell effector functions are modified during progression of chronic viral hepatitis to cirrhosis." (PMID 37006304, 2023). "In a prospective clinical analysis, human patients with HCC but not cirrhosis had increased plasma levels of CCL2 and IL13 that was associated with invasive and multifocal disease." (PMID 31933479, 2020). "Both CCL2 (p=0.006) and IL13 (p<0.0001), were significantly elevated in the plasma of patients with HCC but not cirrhosis." (PMID 31933479, 2020). "Finally, in the plasma of patients with HCC (n = 25) but not cirrhosis (n = 10), CCL2 and IL13 were increased and IL13 predicted invasive tumors." (PMID 31933479, 2020).
Hodgkins lymphoma (12 papers, 2013 to 2025). A heterogeneous group of malignant lymphoid neoplasms of B-cell origin characterized histologically by the presence of Hodgkin and Reed-Sternberg (HRS) cells in the vast majority of cases. "IL-13-positive mast cells are present in the nodular sclerosis subtype of classical Hodgkin’s lymphoma and are associated with a higher degree of fibrosis." (PMID 36430483, 2022). "It is interesting to note that Hodgkin lymphoma is often found in patients with autoimmune problems and is associated with abnormalities in IL-13 signaling, a cytokine produced by mast cells, eosinophils, nuocytes, and Th2 cells." (PMID 35773312, 2022). "Signal transducer and activator of transcription 6 (STAT6), which is activated by IL-13, was found to be phosphorylated in cell lines of Hodgkin lymphoma." (PMID 35685639, 2022). "TGF-β- and IL-13-positive MCs were observed in human biopsies of the nodular sclerosis subtype of classical Hodgkin lymphoma (CHL)." (PMID 35159157, 2022). "In Hodgkin's lymphoma (HL), IL-13 promotes proliferation and inhibits cells death through STAT6 activation." (PMID 27533463, 2016). "In accordance with our observations, it has been reported that IL-6 is expressed by cervical carcinoma cells infected with HPV and, on the other hand, IL-13 expression was demonstrated in cell lines derived from Hodgkin disease and pancreatic cell lines." (PMID 25309919, 2014). "IL-13 has been shown to be expressed by cell lines of Hodgkin lymphoma." (PMID 35685639, 2022). "In addition, IL-4-binding fusion protein APG598 and IL-4R antagonist APG201 (R121D/Y124D) improved the chemosensitivity of Hodgkin lymphoma cells, which indicates that the combination of classical chemotherapy with IL-4/IL-13 antagonists may improve the efficacy of the both in cancer treatments." (PMID 33804263, 2021). "HDAC11 negatively regulated the expression of interleukin-13/17 (IL-13/17) and tumor necrosis factor-alpha (TNF-α) in Hodgkin lymphoma, suggesting that HDAC11 inhibitors killed tumor cells by activating inflammatory responses, immune system activity, and apoptosis processes." (PMID 40421455, 2025). "This, in turn, might induce the production of IL-13 and TGF-β (probably by MCs), resulting in the observed fibrosis of the nodular sclerosis subtype of CHL." (PMID 35159157, 2022).
Hypertension (12 papers, 2008 to 2024). The presence of chronic increased pressure in the systemic arterial system. "IL-6 and IL-13 levels significantly decreased in combined hypertension disorders when compared with normal pregnant women." (PMID 28348564, 2017). "Assuming that inflammation may be the underlying mechanism in the relationship between MASLD and hypertension, we evaluated cytokines (TNF-α, IL-6, IL-10, IL-4, and IL-13) in the liver of patients with morbid obesity, MASLD, and SAH compared to patients without SAH." (PMID 39337863, 2024). "If variant alleles in IL8 and IL13 SNPs alter protein expression and have an effect on VEGF-R2, a stronger inhibition of VEGF-R2 in the concomitant presence of sunitinib would explain our results on a higher risk for any toxicity, including hypertension and leukopenia." (PMID 26387812, 2015). "Cytokine/chemokine IL-1ra, IL-6, IL-13, IFN-γ, MCP-1, MIP-1β levels and metabolic hormone such as GLP-1 levels significantly (p < 0.05) decreased in pregnant women with hypertensive disorders as compared with the HP group." (PMID 28348564, 2017). "In individual hypertension disorders, significantly lower levels of IL-6 and IL-13 were observed only in the GH group but not in PE and EC groups when compared with normal pregnant women." (PMID 28348564, 2017).